MIF (macrophage migration inhibitory factor)
Diseases named in the same sentence as MIF in open-access papers (continued):
Sharing a sentence is not in itself a finding about the gene and the disease.
myocardial infarction (continued). "Most importantly, the admission MIF level in patients with STEMI was found to be correlated to the size of the myocardial infarction, and further, our previous study has shown that admission MIF levels can predict both in-hospital mortality and long-term MACCE." (PMID 36035926, 2022). "Recently, we showed that hypoxia induction and macrophage migration inhibitory (MIF) modification could improve the therapeutic effects of MSC-derived exosomes in myocardial infarction (MI) by inhibiting apoptosis and promoting angiogenesis." (PMID 35870960, 2022). "This could be the reason why MIF levels in the early stage of STEMI patients were related to the final myocardial infarction area." (PMID 30983881, 2019). "Circulating MIF levels increase early in patients with myocardial infarction and can reflect the myocardial infarct size; however, the relationship between MIF levels and acute and chronic cardiac function after infarction remains unclear." (PMID 30983881, 2019). "Novel chemical inhibitors of MIF and MIF-2 in myocardial infarction models remain to be tested." (PMID 30983881, 2019). "Animal experiments demonstrated that the main source of MIF in the early phase after myocardial infarction is necrotic cardiomyocytes and its secretion pattern is characterized by direct, massive, and rapid release under ischemic stimulation, which is not dependent on de novo synthesis." (PMID 30983881, 2019). "Upregulation of MIF also contributes to acute myocardial infarction and heart dysfunction." (PMID 30483634, 2017). "Although still unclear, the current evidence suggests that some inflammatory cardiomyopathies (e.g., iatrogenic cardiomyopathy) may benefit from MIF signaling, which coincides with the reported function of MIF in studies investigating myocardial infarction and remodeling." (PMID 40092999, 2025). "Salidroside is a potential therapeutic agent for myocardial infarction (MI), exerting therapeutic effects on macrophage migration inhibitory factor (MIF)-regulated mitochondrial quality control." (PMID 40016840, 2025). "(B) MIF involvement and the role of metabolic and regulatory processes in myocardial infarction (MI) and ischemia–reperfusion injury (I/R)." (PMID 39202723, 2024). "The data from this study not only suggest that MIF can be used as a biomarker in the clinical setting but also suggest that MIF could be a promising therapeutic target candidate in preventing cardiac dysfunction after acute myocardial infarction." (PMID 30983881, 2019). "Macrophage migration inhibitory factor (MIF) is a pleiotropic cytokine known to play a major role in inflammatory diseases such as myocardial infarction (MI), where its expression increases." (PMID 30678084, 2019). "However, it remains to be demonstrated experimentally whether MIF-2 is activated in acute myocardial infarction in a similar manner as MIF." (PMID 30983881, 2019). "In myocardial infarction (MI), myocardiocyte-secreted MIF exerts a protective effect when cardiac ischemia is brief by activating AMP-activated protein kinase (AMPK) and stress suppression." (PMID 27014277, 2016). "Furthermore, researchers have shown that circulating MIF levels are increased during myocardial infarction but diminished during aging, suggesting that MIF-mediated signaling and its protective effects are active during cardiac ischemia but impaired by senescence." (PMID 25896286, 2015). "Macrophage migration inhibitory factor (MIF) can rejuvenate senescent MSCs by activating autophagy and enhancing their therapeutic efficacy for myocardial infarction." (PMID 33330487, 2020). "Myocardial infarction patients are known to have elevated plasma levels of MIF, which are predictive for infarct size, but the molecular actions of MIF and its role during MI remain unclear." (PMID 30678084, 2019).
myocardial infarction (continued). "MIF levels were sharply elevated in first obtainable blood sample from ST-segment elevation myocardial infarction (STEMI) patients and the raised MIF can predict the ultimate area of myocardial infarction (MI) and the degree of adverse cardiac remodeling." (PMID 33850223, 2021). "There is evidence that MIF can also affect interstitial fibrosis in noninfarcted areas after myocardial infarction." (PMID 30983881, 2019).
dengue (34 papers, 2010 to 2025). "In DENV infection, increased levels of MMP-2, MMP-9, and MIF have been associated with increased risk of dengue severity, and both MMP-9 and MIF were reported to induce vascular hyperpermeability." (PMID 34882753, 2021). "The first evidence of the pathogenic role of MIF in dengue disease was indicated by the positive correlation between the MIF level in the sera of dengue patients and disease severity." (PMID 32545679, 2020). "However, MIF is up-regulated in serum and correlates with a severe clinical presentation and a risk of fatal outcome in dengue, which is a systemic flavivirus infection, suggestive of its role in the pathogenesis of flavivirus meningitis/encephalitis as well." (PMID 28646884, 2017). "MIF inhibits migration of dengue virus-infected macrophages to limit virus spread but is also involved in pathogenesis of dengue virus infection, including an overactive inflammatory cytokine response, viral replication, vascular permeability and leakage." (PMID 36110852, 2022). "High levels of macrophage migration inhibitory factor (MIF) is observed in Dengue haemorrhagic patients and has been suggested to increase the expression of thrombomodulin and ICAM-1." (PMID 35864519, 2022). "In a murine dengue model, inhibition of MIF abolished NS-1-induced MMP-9 secretion, and this correlated with reduced syndecan-1 shedding, suggesting that MIF is an important factor that mediates vascular pathology in DENV infection." (PMID 34882753, 2021). "Since MIF is involved in dengue pathogenesis, the therapeutic potential of blocking MIF to protect against dengue disease has also been studied." (PMID 32545679, 2020). "The serum level of MIF is known to be positively correlated with another life-threatening viral infection, Dengue fever, as MIF is involved in the viral replication of Dengue and in many pathological changes such as vascular leakage." (PMID 33584306, 2020). "MIF plays crucial roles in dengue pathogenesis; however, targeting only MIF secretion and expression seems to be insufficient to provide full protection against DENV infection." (PMID 32545679, 2020). "In patients coinfected with HIV, plasma levels of MIF and IL-1RA remained increased after recovering from dengue illness, which is consistent with persistent inflammation in HIV infected subjects under stable ART." (PMID 31068600, 2019). "Similar to previous reports, the pro-inflammatory cytokines IL-1β, IFN-γ, TNF-α and MIF were increased in plasma samples from patients with dengue at the acute phase compared to samples obtained after recovery." (PMID 31068600, 2019). "MIF has a broad range of immune and pro-inflammatory activities, and has been reported to be correlated with the severity of dengue disease." (PMID 29445153, 2018). "The concentrations of CD138 and MIF were significantly elevated in the serum of severe dengue patients compared to dengue patients with warning signs." (PMID 29702687, 2018). "DENV infection can induce MIF secretion, and the concentration of MIF is positively correlated with dengue severity." (PMID 29702687, 2018). "In fact, several clinical studies have shown that the MIF concentration is elevated in dengue patients and that the MIF concentration is higher in DHF patients who die than in DHF survivors and DF patients." (PMID 30037331, 2018). "To determine if other biomarkers of monocyte and macrophage activation had any association with the severity of dengue disease, we assessed plasma levels of LPS binding protein (LBP), sCD14, sCD163, MIF, MCP-1 and MIP-1b in the three study groups." (PMID 28569153, 2017). "Previous studies have indicated that elevated serum levels of MIF, sVCAM-1, sFas, sFasL, and IFN-γ are associated with dengue." (PMID 27549428, 2016). "Elevated mRNA levels of MIF and decreased mRNA level of thrombospondin-1 were observed in dengue patients (including dengue fever and dengue hemorrhagic fever)." (PMID 27549428, 2016).
dengue (continued). "Nevertheless, it is known that the serum levels of MIF in dengue patients correlate with disease severity and clinical outcome." (PMID 25821355, 2015). "MIF is a critical mediator of the host immune response and inflammation, and there is a correlation between the serum levels of MIF and disease severity in dengue patients." (PMID 25821355, 2015). "As dengue is a very dynamic disease, we determined serum IL-10 levels and MIF levels in 65 patients during the febrile phase and critical phase, hoping to gain a better insight into how these cytokines change in patients with SD and non SD." (PMID 23883139, 2013). "Serum IL-10 and MIF levels were determined in 65 patients (7 of them with severe dengue) in both the febrile phase and the critical phase." (PMID 23883139, 2013). "In contrast, serum MIF levels were significantly higher (p = 0.007) in patients with secondary dengue (mean 115,276, SD ± 538,567) when compared to those with primary dengue (mean 12669, SD ± 8.240)." (PMID 23883139, 2013). "Secondly, preliminary studies have proposed a key role for macrophage migration inhibitory factor (MIF) in dengue pathogenesis." (PMID 22458265, 2012). "A deleterious role of MIF was recently observed in a mouse model of lethal dengue virus infection, with reduced systemic inflammatory response in Mif−/− mice compare to wt mice." (PMID 21977228, 2011). "Furthermore, it has demonstrated that severe dengue virus infections induce the expression of macrophage migration inhibitory factor (MIF), which in turn stimulates monocytes and endothelial cells to express higher levels of ICAM-1." (PMID 41313499, 2025). "Treatment with MIF neutralizing antibodies or inhibitors may provide protection against dengue disease." (PMID 32545679, 2020). "Studies focusing on the development of neutralizing antibodies or small molecules against MIF may facilitate the development of drugs to prevent or treat severe dengue." (PMID 29702687, 2018). "However, only the concentrations of NS1 and MIF showed a positive correlation with CD138 in severe dengue patients." (PMID 29702687, 2018). "Furthermore, Mif−/− mice exhibited reduced pathogenesis in a model of severe dengue, indicating the importance of MIF in dengue pathogenesis." (PMID 30037331, 2018). "Chuang’s research showed that MIF induced by Dengue virus infection activates endothelial cell tight junction opening, which may cause plasma leakage and leukocyte migration (extravasation), resulting in increased vascular permeability." (PMID 29482504, 2018). "Only NS1 and MIF showed a positive correlation with CD138 in the sera of severe dengue patients." (PMID 29702687, 2018). "It suggests that serum resistin and sFasL might be potential biomarkers for dengue infection since MIF is correlated with disease severity and clinical outcome in dengue." (PMID 27549428, 2016). "Therefore, MIF secretion can be induced by either DENV infection or NS1 stimulation of different cells in dengue patients." (PMID 27409803, 2016). "Several studies have shown that serum IL-10, IFNγ and MIF are elevated in patients in severe dengue (SD) and could be used as potential biomarkers." (PMID 23883139, 2013). "Compared to wild-type mice, dengue-infected MIF -/- mice show decreased macrophage viability, decreased proinflammatory function and increased apoptosis, which results in lower viral load, less severe clinical manifestations and a significant delay in lethality." (PMID 22458265, 2012). "As patients with dengue hemorrhagic fever show elevated plasma concentrations of MIF, it is possible that neutralizing MIF activity may have a role in the treatment of severe dengue in humans." (PMID 22458265, 2012). "In addition, MIF may modulate the interaction of different immune cells, which contributes to dengue pathogenesis." (PMID 32545679, 2020).
dengue (continued). "The variable expression of MIF has been shown to correlate with the clinical course of infectious diseases, suggesting its involvement in response to pneumonia and viral meningitis, but also detrimental effects of its over-expression in purulent meningitis and dengue." (PMID 28646884, 2017). "Therefore, we proposed and tested the hypothesis that dengue NS1 increases vascular permeability through MIF secretion and autophagy formation." (PMID 27409803, 2016). "MIF release by neutrophils leads to neutrophil extracellular trap (NET) formation and inflammation which further helps in dengue pathogenesis." (PMID 33102253, 2020). "We found that the levels of MIF, HPA-1, MMP-9, and CD138 were all increased in the serum of dengue patients." (PMID 29702687, 2018). "In this study, we first observed that the concentrations of NS1, MIF, HPA-1, MMP-9 and CD138 in the serum of dengue patients were increased." (PMID 29702687, 2018). "Serum levels of MIF, sVCAM-1, sFasL, resistin and IFN-γ in dengue patients were significantly higher than those in healthy controls." (PMID 27549428, 2016). "Our results showed the serum concentrations of MIF, sVCAM-1, sFasL, resistin, and IFN-γ were significantly higher in dengue patients than that in healthy controls." (PMID 27549428, 2016). "Information on lymphocyte and platelet counts, levels of IL-10 and MIF, levels of AST and ALT, levels of gene expression and cell free DNA will aid in predicting severe dengue." (PMID 26462910, 2015). "Recent clinical correlative studies have demonstrated increased MIF levels and elevated MIF-dependent proinflammatory cytokines are produced during H1N5 influenza infection, dengue fever, and bacterial urinary tract infections." (PMID 20361053, 2010). "In dengue virus infections, serum MIF levels have been shown to correlate with disease severity, with higher levels in patients who died of dengue hemorrhagic fever (DHF) than in patients who survived DHF and patients with mild dengue fever." (PMID 38275363, 2023). "The earlier studies included few markers of severe form of dengue like plasmacytoid and dendritic cells, cytokines like IFN gamma, TNF alpha, IL 6, IL 10, MIF; chemokines like CXCL 10; complements like C3a, C5a; proteases like tryptase and chymase." (PMID 36091089, 2022). "Our first priority was to compare the levels of IL-1b, IL-2, IL-4, IL-6, IL-8, IL-10, IL-12p70, IL-17A, IL-33, CD14, CD54, CD62E, CD62L, CD62p, CD106, CD121b, CD154, CD178, GM-CSF, IFN-g, MIF, ST2 and TNF in plasma samples of dengue group, OF group and Healthy group." (PMID 33809042, 2021). "Macrophage migration inhibitory factor (MIF) is a pleiotropic proinflammatory cytokine that mediates diverse immune responses, and the serum level of MIF positively correlates with disease severity in patients with dengue." (PMID 32545679, 2020). "In this study, we observed that among NS1, MIF and glycocalyx degradation-related molecules, the HPA-1, metalloproteinase 9 (MMP-9) and syndecan 1 (CD138) serum levels were all increased in dengue patients, and only NS1 and MIF showed a positive correlation with the CD138 level in severe patients." (PMID 29702687, 2018). "Serum samples from severe dengue patients also showed no linear relationship between the concentrations of MIF and HPA-1." (PMID 29702687, 2018). "Taken together, these results suggest that MIF directly engages in dengue NS1-induced glycocalyx degradation and that targeting MIF may represent a possible therapeutic approach for preventing dengue-induced vascular leakage." (PMID 29702687, 2018). "Studies show that elevated levels of IL-6, IL-10, IFN-γ, MIF, and CCL-4 could be used as potential predictors of severe dengue." (PMID 27903271, 2016). "Some have shown that MIF, IL-10, IL-6, MIP-1ß and IFNγ could be used as potential predictors of severe dengue." (PMID 23883139, 2013).
dengue (continued). "Therefore, the release of MIF from neutrophils may induce NET formation and inflammation in DENV infection, which contributes to dengue pathogenesis." (PMID 32545679, 2020). "Increased levels of TNF-α, IL-1β, IL-4, IL-6, IL-8, IL-13, IL-15, macrophage migration inhibitory factor (MIF), and chemokines CCL2, CCL4, CCL5, and CXCL10 (IP-10) among others, have been reported in patients with dengue hemorrhagic fever (DHF) when compared to dengue fever (DF)." (PMID 29986388, 2018). "Thus MIF may contribute to inflammation and hemostatic abnormality during DENV infection and there is a correlation between MIF serum levels and disease severity in dengue patients." (PMID 28746373, 2017). "In these studies, IL-1ß, IFN-γ, IL-4, IL-6, IL-13, IL-7, GM-CSF (Granulocyte-macrophage colony-stimulating factor), MIF (macrophage migration inhibitory factor), IL-10 along with several other cytokines have been found to be elevated in patients with DHF when compared to dengue fever (DF)." (PMID 23883139, 2013).